IL10 (interleukin 10)
Diseases named in the same sentence as IL10 in open-access papers (continued):
Sharing a sentence is not in itself a finding about the gene and the disease.
asthma (continued). "In addition, the subcutaneous application of β-1,3-glucan extracted from Saccharomyces cerevisiae in 20 children with asthma increased serum levels of the anti-inflammatory cytokine IL-10 and simultaneously reduced symptom scores." (PMID 32751743, 2020). "However, the role of IL-10 in the regulation of Th2-mediated diseases such as asthma is controversial." (PMID 33265990, 2020). "Furthermore, IL-17/IL-10 ratio was remarkably enhanced in the patients of asthma exacerbation, which implied that Th17 cells and Treg cells didn’t keep balance." (PMID 33013382, 2020). "One and 5 μg/ml BioPM collected from chicken, goat and pig farms induced the production of IFNγ, IL-10, IL-1β and TNFα by PBMCs from stable asthma patients and healthy volunteers in an apparent concentration-dependent manner (except for TNFα production induced by BioPM from the goat farm)." (PMID 32620109, 2020). "It has been demonstrated that IL-10 plays an important role in controlling asthma." (PMID 33584704, 2020). "This may indicate that MDSCs and IL-10 could play a role in the pathogenesis of asthma, suggesting additional investigations." (PMID 32931721, 2020). "Interestingly, although IL‐27 production was increased in the IfitmF–/– mice compared to WT in our asthma experiments, levels of Il4, IL‐5, IL‐13, IL‐6, IL‐10, IL17, and TNF‐α were all decreased." (PMID 30365177, 2019). "Different allele and genotype variations alter cytokine profiles influencing the development and severity of various diseases, as documented in SLE, tuberculosis and several other infectious diseases (IL-10 overexpression), and rheumatoid arthritis and asthma (IL-10 downregulation)." (PMID 30779760, 2019). "In allergic rhinitis and asthma, airway IL-10 expression is reduced." (PMID 31852975, 2019). "Dexa and MYR both increased the level of IL-10 compared to the asthma group (P < 0.05)." (PMID 32641957, 2019). "For example, the combination of IL-10 or IL-2 with Treg or TFR cells may synergize the immuno-suppressive function of pathogenic TFH cells and confer improved control of asthma symptoms in patients." (PMID 31921177, 2019). "However, our results support the additional involvement of IL-10, a potent suppressor of total and allergen-specific IgE responses, as seen in immunotherapeutic protocols used in murine models of asthma." (PMID 31611876, 2019). "Increasing the concentration of rhIL-2 in the presence of dexamethasone maintained elevated levels of IL-10 while reducing the IL-17A response, which may provide new avenues for the development of improved clinical therapies for asthma." (PMID 30598515, 2019). "This suggests that IL-10, because it is an anti-inflammatory cytokine, may act to inhibit cell migration and attenuate the local inflammatory response observed in asthma." (PMID 31015955, 2019). "The level of IL-10 decreased in the lung tissue of the asthma group (P < 0.001)." (PMID 32641957, 2019). "We are the first to show the higher CG methylation content of the LMO2 or IL10 is correlated to prenatal exposure of PTS, and the combination of LMO2_E148 (≧28.5%), IL10_P325 (≧38.5%), and GSTM1_P266 (≧41.5%) reveals the highest risk to childhood asthma." (PMID 31214241, 2019). "However, asthma-induced susceptibility is also observed in IL-12−/− and IFN-γR−/− mice, suggesting that asthma-induced IL-10 affects IL-12 independent effector mechanisms controlling Brucella in the lungs." (PMID 30147700, 2018). "After AOS treatment, IL-10 may inhibit the antigen-presenting process and T cells response and play a critical role in the prevention of asthma." (PMID 30294594, 2018). "In the pathogenesis of asthma, Treg cells secrete a variety of cytokines that can suppress the proliferation of T cells and the synthesis of IgE through the transmission of inflammatory cells, such as IL-10 and TGF-β." (PMID 30294594, 2018).
asthma (continued). "To further clarify whether the WTD can adjust the apoptosis state of EOS to achieve the purpose of alleviating asthma, we use ELISA method to detect IL-5, IL-10, CSF, CCL5, TGF-β, and IFN-γ in rat serum." (PMID 29713367, 2018). "While IL-10 is up regulated in mild asthma patients, it decreased in severe asthma patients." (PMID 30915130, 2018). "Intriguingly, knockdown of this miRNA in an established allergic airway inflammation significantly alleviated most of the features of asthma such as airway hyperresponsiveness, increased Th2 response, and sub-epithelial fibrosis, along with increased IL-10 levels in the lungs of male mice." (PMID 29739446, 2018). "In summary, serum IL-4, IL-5 and IL-10, adhesion molecules, and sE-selectin were all involved in the pathogenesis of allergic rhinitis and asthma, which can be used to diagnose the degree of respiratory allergic diseases, thus being potentially applicable to clinical practice." (PMID 30344593, 2018). "Therefore a picture emerges of asthma being a disease in which homeostatic control of inflammation by IL-10+ M2-like macrophages is lost due to polarisation towards M1 and/or M2." (PMID 29572536, 2018). "Oxidative stress has also been shown to contribute to corticosteroid resistance, a major feature of severe asthma, and we have previously shown that vitamin D exerts a steroid-sensitising action in severe asthma, restoring dexamethasone-induced IL-10 production by T cells." (PMID 30157189, 2018). "Even though IL10 is a regulatory cytokine with immunosuppressive and anti-inflammatory properties, its role in asthma remains unclear." (PMID 29272313, 2017). "Moreover, the levels of IFN-γ, IL-4, and IL-17A in serum, lung tissue, and BALF of C5aRA-treated RSV-infected asthma mice were also decreased, while the levels of IL-10 were increased." (PMID 29123203, 2017). "Similarly, mTOR inhibitor treatment during asthma onset restored IL-4, IL-10, and IFN-γ levels to levels similar to those in the control mice." (PMID 28674387, 2017). "Similarly, plasma IFN-λ2 positively correlates with tryptase, and IL-10 positively correlates with IL-12 in asthma." (PMID 27057098, 2016). "IL-10 levels are lower in patients with acute lung inflammation, asthma, COPD, or cystic fibrosis than in healthy individuals, and this deficiency may contribute to pathogenesis." (PMID 26475448, 2016). "Furthermore, Smteg/asthma mice showed high percentage of CD11b+F4/80+IL-10+ and CD11c+CD11b+IL-10+ cells in lungs." (PMID 27454771, 2016). "Interleukin-10 produced by Tregs constitutes one of the main suppression mechanisms during asthma." (PMID 28066430, 2016). "The percentages of IL-10+γδT lymphocytes were similar in the asthma and normal control groups." (PMID 27518187, 2016). "The results showed that the levels of IFN-λ2 were elevated by 17.9% and 14.2% in the plasma of allergic rhinitis (AR) and combined rhinitis with asthma (AR + AS), which was positively correlated with the level of tryptase but negatively correlated with the level of IL-10." (PMID 27057098, 2016). "This may also be why some relief from EIA may be obtained with asthma controller treatment therapies such as inhaled corticosteroids, which are known to upregulate IL-10 production, in addition to other important anti-inflammatory effects." (PMID 27524866, 2016). "In our study, the level of IL-10 decreased after 12 weeks of TCM treatment, suggesting that TCM may inhibit airway inflammation by reducing the secretions of IL-10 to control asthma attacks." (PMID 27378824, 2016). "In this murine asthma model, we detected the expression level of IL-10 in splenocytes." (PMID 26495021, 2015). "Furthermore, as predicted from our earlier work, cells from the calcitriol-treated patients with SR asthma now showed a significant increase in IL-10 production in response to dexamethasone, an effect that was most marked in the presence of IL-4 in culture." (PMID 25772594, 2015).
asthma (continued). "However, currently, there is limited information on the role of suppressor IL-10 in the anti-inflammatory feedback on innate antiviral immune response in the lung in virus-induced asthma." (PMID 25430775, 2015). "In human asthma studies, there is evidence suggesting that the dominant MØ phenotype in atopic asthmatic subjects is alternatively activated (aaMØ or M2), characterized by increased production of IL-10." (PMID 25430775, 2015). "Although some knowledge has accumulated on the association between cytokines or cytokine genetics, such as IL-10 polymorphisms, and wheezing or asthma in preschool-aged children, no lung function studies have so far been published." (PMID 26473365, 2015). "On the other hand, Tregs (regulatory T lymphocytes) could also be a source of IL-10, although these cells are less functional and their numbers are reduced in asthma." (PMID 26362930, 2015). "Recent reports indicated that the use of IL-10-targeted experimental therapies could provide protection against asthma in mouse model of this disease." (PMID 24865466, 2014). "The IL-2:anti-IL-2 treatment is dependent on Treg-derived IL-10, and suggests that endogenous Treg therapy may be a useful tool to combat asthma." (PMID 24886492, 2014). "Severe inflammation induces the production of IL-10 by MDSCs, which down-regulates the level of IL-12, therefore we speculate that MDSCs plays an important role in the onset of asthma through up-regulating IL-10 and down-regulating IL-12." (PMID 23717481, 2013). "High level of IL-10 is often observed in virus-induced asthma attack, which is consistent with the elevated IL-10 we observed in this study, as many cases in the asthma attack group was detected positive for respiratory virus (Respiratory Syncytial Virus and Rhinovirus)." (PMID 23717481, 2013). "In severe asthma, Tbet expression was strongly correlated with Il2, Il6, and Il10 expression." (PMID 23781124, 2013). "Currently, the role of IL-10 in asthma pathogenesis is still under debate." (PMID 23717481, 2013). "Studies on the resolution of asthma may reveal whether an increased production of IL-10 by these macrophages is involved." (PMID 23533311, 2013). "Of particular interest, Il10 showed the largest change in mRNA expression in mild asthma." (PMID 23781124, 2013). "Recently, it was reported that IL-10 and IL-12, important cytokines secreted by helper T lymphocytes, may play important roles in the pathogenesis of asthma." (PMID 23717481, 2013). "In severe asthma, allergen sensitization and challenge increased Il6, Il5, and Il10 expression." (PMID 23781124, 2013). "Further, HLA-G production may in turn be regulated by the pleiotropic, immunoregulatory cytokine IL-10 which may in the context of asthma further regulate T cell profiles and function." (PMID 23327606, 2013). "Low levels of IL-10 expression have a role on the pathogenesis of asthma." (PMID 23335974, 2013). "This suggests that specific stimulation of macrophages to polarize to M2-like macrophages that produce IL-10 may reduce asthma symptoms." (PMID 23533309, 2013). "Therefore, we suspect that both granulocytic (CD11b+Ly6G+Ly-6C low) and monocytic (CD11b+Ly-6G-Ly-6GC high) MDSCs contribute to the production of IL-10 during the onset of asthma." (PMID 23717481, 2013). "These macrophages could play an important role in the resolution of asthma because of their production of IL-10." (PMID 23533311, 2013). "Acupuncture has also been found to significantly reduce IL-6 and IL-10 in humans with asthma." (PMID 23476696, 2013). "Moreover, macrophages from severe asthmatics produce high levels of IL-6 and IL-8, but IL-10 was undetectable in these cells compared to macrophages from patients with moderate asthma." (PMID 23533311, 2013). "A recent study demonstrated IL-10 producing CD1dhigh B cells from the spleens of schistosome infected mice could transfer immune regulation in a mouse model of ovalbumin-induced asthma." (PMID 23429492, 2013).
asthma (continued). "In summary, these findings suggest that DC/OVA-Dll4 treatment might induce protective immunity against asthma through induction of IL-10 or IFN-γ production by OVA-specific T cells." (PMID 23696838, 2013). "Therefore, we propose that MDSCs play a role in asthma pathogenesis by up-regulating IL-10 and down-regulating IL-12." (PMID 23717481, 2013). "Asthma patients treated with antigen specific immunotherapy showed increased IL-10 and suppressed T cells; however, T cell proliferation and cytokine secretion was completely restored upon neutralization of IL-10 in the peripheral blood of these asthma patients." (PMID 23717481, 2013). "We then analyzed the accumulation of IL-10 to study the possible mechanism of asthma onset in mice." (PMID 23717481, 2013). "MDSC accumulation and serum IL-10 levels were significantly elevated in the children with asthma compared with the budesonide-treated alleviated group, normal healthy controls, and pneumonia controls (p<0.05), whereas those in the latter three groups showed no statistical differences (p>0.05)." (PMID 23717481, 2013). "Our data from asthma patients and asthma mouse models indicate that the interaction between MDSCs and macrophages leads to a significant increase in the levels of IL-10 and decrease in levels of IL-12, which promote the development of chronic inflammation seen in asthma." (PMID 23717481, 2013). "In a mouse model of asthma IL-10 was shown to act as an anti-inflammatory." (PMID 23533311, 2013). "We have just shown that the number of IL-10-positive cells is lower in lungs of mice with house-dust-mite-induced asthma as compared to control mice, and recently it was also shown that lung interstitial macrophages produce high levels of IL-10 and prevent airway inflammation in mice." (PMID 23533311, 2013). "In addition, IL-10 secreted by NKT cell in the asthma group was significantly decreased compared with the normal control group (P < 0.01), especially at 48 hours, and the IL-10 of SIT group significantly increased compared with asthma patients (P < 0.01)." (PMID 23008731, 2012). "However, asthma and COPD-associated pathogenic bacteria provoked a 3–5 fold higher production of IL-23, IL-12p70 and IL-10 cytokines compared to the commensal bacteria." (PMID 22363778, 2012). "The elevated level of IL-10 in the serum of asthma subjects indicated an increase in Type-2 activity through which the production of IL-4 and IL-13 may promote an isotype switch to IgE." (PMID 23226977, 2012). "Moreover, the function of Treg cells is impaired in asthma patients, and therefore an increase in IL-10 production seems by definition beneficial for this patient group." (PMID 23091602, 2012). "In addition, IL-10 is crucial for the Th2-polarized responses in asthma and has a regulatory role in the later immune responses by down-modulating the inflammation caused by Th2 cell signaling." (PMID 22855687, 2012). "Additionally, oral administration of ScLL reduced IL-4 and IL-5 levels in murine models of acute and chronic inflammation and lead to increased IFN-γ and IL-10 production in asthma inflammatory model, directing a shift from Th2- to Th1-biased immune response." (PMID 23107170, 2012). "As such, the increased Treg cell counts and IL-10 production might fit the paradigm that sitostanol can rebalance the disturbed Th1/Th2 balance in asthma patients." (PMID 23091602, 2012). "In our study, lower concentrations of IL-10 were observed in CVA patients and mild asthmatics compared with control subjects, suggesting the existence of deficient immune regulation in cough variant asthma as well as classic asthma." (PMID 22927709, 2012). "There have been conflicting reports in literature on the levels of IL-10 in asthma patients." (PMID 23226977, 2012). "Furthermore, a molecular phenotype characterized by the presence of CXCL1, RANTES, IFNγ, IL-12 and IL-10 separated children with severe asthma from those with moderate asthma." (PMID 22168152, 2011).
asthma (continued). "However, if cytokine data in a population report that IL-10 and IFN-γ are at risk for allergy and asthma, the confounding effects of Th2 cytokines should be accounted and the corresponding findings should be interpreted with caution." (PMID 23724228, 2011). "In asthma we found a positive association of IL-4 with IL-5, and significant association with IL-13, TNF α as well as GM-CSF, while IL-5 is positively associated with IL-4, IL-10 and GM-CSF." (PMID 20616938, 2010). "Vitamin D has also been noted to modulate Treg function and IL-10 production, which may increase the therapeutic response to GC in GC-R asthma." (PMID 23675190, 2010). "To test our hypothesis we measured serum concentrations of eleven cytokines and chemokines that were recently described to play an important role in asthma pathogenesis: IL-4, IL-5, IL-8, IL-10, IL-12 (p40), IL-13, IL-17, TNFα, GM-CSF, eotaxin, and IFNγ." (PMID 21179211, 2010). "There is increasing evidence that IL-10 secretion, in particular by Treg, may be defective in patients with asthma." (PMID 21197090, 2010). "In addition, lower concentrations of IL-10 in bronchoalveolar lavage (BAL) fluid or in induced sputum were found in subjects with asthma." (PMID 21197090, 2010). "For IL10, none of the SNPs associated with asthma in the SLSJ study were significant in the other studies except the promoter polymorphism rs1800896, with a marginal p value of 0.022 in CAPPS." (PMID 19852851, 2009). "In this model, the risk of asthma is similar for carriers of two common CD86 alleles irrespective of the IL10 genotypes, however, the risk increases additively with the number of rare alleles in the two genes." (PMID 19852851, 2009). "Again modest associations were observed for the IL10, CYP24A1 and CD86 genes for asthma or atopy." (PMID 19852851, 2009). "Only asthma patients had an increased in IL-10 after DE exposure." (PMID 19630984, 2009). "In this model, the risk of asthma increased additively with the number of G alleles (tagging the high-risk/high-expressed haplotype) at the VDR locus and with the number of T alleles (tagging the high-risk/low-producing haplotype) at the IL10 locus." (PMID 19852851, 2009). "The potent immunosuppressive and anti-inflammatory action of IL-10 has suggested that it may be useful therapeutically in the treatment of asthma." (PMID 18315837, 2008). "Recent data also suggests that vitamin D3 in conjunction with a glucocorticoid may restore the reduced expression of Il-10 seen in T-cells from patients with severe asthma." (PMID 18315837, 2008). "Furthermore, a defect in glucocorticoid-induced IL-10 production has also been described in blood T lymphocytes from patients with glucocorticoid-resistant asthma." (PMID 18315837, 2008). "IL-10 concentrations are reduced in induced sputum from patients with asthma or COPD, indicating that this might be a mechanism for increasing lung inflammation in these diseases." (PMID 18315837, 2008). "The attenuated IL-10 production in eNOS mice might contribute to the reduced development of asthmatic features in this asthma model." (PMID 16597326, 2006). "IL4 and IL10 has long been investigated as potential candidate genes for asthma and atopy." (PMID 16759385, 2006). "SNPs in 5 genes showed a p-value < 0.05 with asthma (IL10, IL12B, VDR, CARD15 and CYP24A1)." (PMID 16600026, 2006). "In addition, the regulating mechanisms of IL-10 and IL-12 for the suppression of experimental asthma are totally different." (PMID 16677403, 2006). "Similarly, B cell-derived IL-10 promoted allergic sensitization during asthma." (PMID 39935481, 2025). "Finally, inhibition of aerobic glycolysis could not only reduce the production of lactate, IL-5, IL-17, and IFN-γ, but also stimulate that of IL-10 and Foxp3 in a mouse model of asthma." (PMID 39040099, 2024).